GPR17 (G protein-coupled receptor 17)
Diseases named in the same sentence as GPR17 in open-access papers (continued):
Sharing a sentence is not in itself a finding about the gene and the disease.
Obesity (6 papers, 2019 to 2026). Accumulation of substantial excess body fat. "Genetic association of GPR17 variants with metabolic deficits is further complicated by the multifactorial etiology of metabolic diseases including type 2 diabetes, cardiovascular diseases, and obesity." (PMID 34144038, 2021). "We reasoned that whole body knockout of GPR17 in mice of the 129 strain might elicit more marked effects because the 129 strain is more susceptible than the C57Bl/6 strain to increased sympathetic activity and less susceptible to high fat diet-induced obesity." (PMID 34646232, 2021). "GPR17-deficient mice and mice with an oligodendrocyte-specific KO of GPR17 are resistant to HFD-induced obesity." (PMID 35055143, 2022). "Genetic mouse models are indispensable for understanding diabetes and obesity pathophysiology, and previous studies in our laboratory and other groups demonstrated the role of Gpr17 in metabolic regulation." (PMID 34144038, 2021). "The fact that Gpr17 knockout produced positive, but unique, metabolic outcomes in Agrp and Pomc conditional knockout mice supports its potential role as a target for obesity therapy." (PMID 31611548, 2019). "By contrast, selective knockout of GPR17 primarily in oligodendrocytes provided protection from high fat diet-induced obesity and knocking out GPR17 in pro-opiomelanocortin neurons attenuated the metabolic effects of high fat diet on body weight and adiposity, most noticeably in female mice." (PMID 34646232, 2021). "Here, we analyzed GPR17 coding sequences from control and disease cohorts consisting of individuals with adverse clinical metabolic deficits including severe insulin resistance, hypercholesterolemia, and obesity." (PMID 34144038, 2021). "Gpr17 deficiency in POMC neurons protects metabolic homeostasis in a sex-dependent manner during dietary and aging challenges, suggesting that Gpr17 could be an effective anti-obesity target in specific populations with poor metabolic control." (PMID 31611548, 2019). "Thus, eliminating the endogenous agonist or supplying antagonists of Gpr17 could be therapeutically relevant strategies for managing obesity." (PMID 31611548, 2019). "In this study, we established that human GPR17 shares similar signaling properties and functions to inhibit GLP-1 secretion, further validating it as a potential target for diabetes and obesity therapy." (PMID 39858405, 2024). "Our study suggests that targeting GPR17 with antagonists or inverse agonists may lead to enhanced GLP-1 secretion and could be an additional approach for treatment of metabolic diseases such as type 2 diabetes and obesity." (PMID 39858405, 2024). "However, whole body knockout of GPR17 in mice of the C57Bl/6 strain did not affect energy balance, whereas selective knockout in oligodendrocytes or pro-opiomelanocortin neurons provided protection from high fat diet-induced obesity and impaired glucose homeostasis." (PMID 34646232, 2021).
demyelinating disease (5 papers, 2017 to 2025). A broad group of disorders that affect the myelin sheaths that cover the neurons. "The mechanism of action of GPR17 antagonists in demyelinating diseases, such as Multiple Sclerosis (MS), is primarily achieved through the regulation of oligodendrocyte differentiation and remyelination." (PMID 41471322, 2025). "Regarding clinical application, substantial evidence supports targeting GPR17 with pharmacological agents to induce myelin repair, thereby representing a potential disease-course-modifying treatment strategy for MS and potentially other demyelinating diseases." (PMID 41471322, 2025). "Globally, this study unveils a functional link between GPR17 expression, lactate release and myelin composition, and suggests that innovative interventions targeting GPR17 may help to foster endogenous myelination in demyelinating diseases." (PMID 35954217, 2022). "This issue is particularly relevant for GPR17, as its role in myelination process, is strictly dependent by the fine modulation of receptor functional responses and may be crucial for the development of new therapeutic strategies in demyelinating diseases." (PMID 36613703, 2022).
ischemia (5 papers, 2008 to 2024). A hypoperfusion of the BLOOD through an organ or tissue caused by a PATHOLOGIC CONSTRICTION or obstruction of its BLOOD VESSELS, or an absence of BLOOD CIRCULATION. "G protein-coupled receptor 17 (GPR17) is a G protein-coupled receptor implicated in the regulation of glial cell differentiation and response in the central nervous system, particularly during repair after brain injury and ischemia." (PMID 39123689, 2024). "Starting from 48–72 h after ischemia, GPR17 immuno-labeling appears on microglia/macrophages infiltrating the injured area." (PMID 18974869, 2008). "We also show that induction of brain injury using an established focal ischemia model in the rodent induces profound spatiotemporal-dependent changes of GPR17." (PMID 18974869, 2008). "Antagonism of GPR17 was reported to attenuate brain tissue damage, suggesting that GPR17 is a potential pharmacological target for the treatment of nervous system diseases, such as ischemia." (PMID 35163437, 2022). "Furthermore, the proposed CysLT receptor GPR17 was found to be up-regulated in damaged tissues, and knockout of the GPR17 gene reduced neuronal injury after ischemia." (PMID 23194405, 2012). "Following ischemia, GPR17 is sequentially induced in neurons, microglia/macrophages and adult oligodendrocyte precursor cells, suggesting that it may act as a common regulatory gene mediating response to injury in embryonically-distinct cell types." (PMID 18974869, 2008). "Finally, no GPR17 co-expression was found in resting microglia detected by anti-Iba1 staining in the intact brain (however, see: “Expression pattern of GPR17 during ischemia evolution”)." (PMID 18974869, 2008).
experimental autoimmune encephalomyelitis (4 papers, 2018 to 2022). An autoimmune demyelinating disease of the central nervous system that is produced experimentally in animals by the injection of homogenized brain or spinal cord in Freund's adjuvant. "Virtual high-throughput screening technology and in vivo assays identified galinex as a GPR17 agonist that significantly delays the onset of experimental autoimmune encephalomyelitis (EAE)." (PMID 34359676, 2021).
Myocardial fibrosis (4 papers, 2014 to 2023). "Inhibition of GPR17 also protects against myocardial fibrosis caused by cardiac ischemia, and we further confirmed that the administration of cangrelor reversed the rise of GPR17 induced by CLP, as well as ameliorating the inflammatory response." (PMID 34229761, 2021). "Modulating GPR17 has shown the potential to improve inflammatory responses and injury, as evidenced by the suppression of microglial activation and inflammation in an ischemic stroke model and the protection against myocardial fibrosis caused by cardiac ischemia." (PMID 37675176, 2023).
amyotrophic lateral sclerosis (3 papers, 2021 to 2024). Amyotrophic lateral sclerosis (ALS) is a neurodegenerative disease characterized by progressive muscular paralysis reflecting degeneration of motor neurons in the primary motor cortex, corticospinal tracts, brainstem and spinal cord. "For example, in an amyotrophic lateral sclerosis (ALS) mouse model, treatment with MTK blocked GPR17 and increased differentiation of OPCs from spinal cord samples." (PMID 39346564, 2024).
cardiac ischemia (3 papers, 2021 to 2023). "Moreover, GPR17, which is a receptor for LTD4 and LTC4, increases the risk of cardiac ischemia through interaction with cardiac CysLT1R." (PMID 36145367, 2022). "Inhibition of GPR17 by MK reduces myocardial ischemia and fibrosis." (PMID 36145367, 2022).
Cognitive impairment (3 papers, 2020 to 2023). Abnormal cognition is characterized by deficits in thinking, reasoning, or remembering. "Finally, in old mice showing typical signs of cerebral degeneration, chronic treatment with another non-selective antagonist (Montelukast) was proved to fully revert the associated cognitive impairment through mechanisms specifically involving GPR17." (PMID 32320409, 2020). "These behavior data indicate that activation of hippocampal GPR17 induced cognitive impairment in normal mice." (PMID 37990234, 2023). "To further verify the role of GPR17 in the regulation of cognitive impairment induced by LPS, we subsequently explored the effects of cangrelor, a GPR17 antagonist, in mice exposed to LPS." (PMID 37990234, 2023). "Gene reduction and pharmacological blockade of GPR17 improved cognitive impairment in both the Morris water maze and novel object recognition tests." (PMID 37990234, 2023). "Herein, we used a mouse model of cognitive impairment induced by lipopolysaccharide (LPS) to further investigate the role of GPR17 in cognition and its potential mechanism." (PMID 37990234, 2023). "Previously we reported that inhibition of GPR17 prevents amyloid β 1–42 (Aβ1-42)-induced cognitive impairment in mice." (PMID 37990234, 2023). "Inhibition of GPR17 with cangrelor ameliorates cognitive impairment and synaptic deficits induced by Aβ1-42 in mice." (PMID 37416324, 2023). "However, activation of hippocampal GPR17 with MDL-29951 induced cognitive impairment in normal mice." (PMID 37990234, 2023). "The purpose of this study was to identify the role of GPR17 on LPS-induced cognitive deficit." (PMID 37990234, 2023). "Therefore, we chose the hippocampal DG as the target region to further investigate the role of GPR17 in cognitive impairment induced by LPS in mice." (PMID 37990234, 2023). "In addition, we also found that activation of hippocampal GPR17 with MDL-29951 induced cognitive impairment in mice." (PMID 37990234, 2023). "Therefore, in this study, we investigated the role and possible mechanism of GPR17 on cognitive deficits induced by LPS in mice." (PMID 37990234, 2023). "In addition, we also found that GPR17 expression was significantly upregulated in the hippocampus of Aβ1–42-induced mouse models of cognitive impairment." (PMID 37990234, 2023). "However, knockdown and inhibition of GPR17 prevented LPS-induced cognitive deficits." (PMID 37990234, 2023). "To verify the functional role of GPR17 in cognitive impairment from the negative side, we used its agonist MDL-29951 to further validate the functional role of GPR17 in learning and memory." (PMID 37990234, 2023). "To date, the effects of GPR17 on LPS-induced cognitive deficits have not been examined." (PMID 37990234, 2023).
ischemic stroke (3 papers, 2021 to 2025). A stroke disorder caused by obstruction of blood flow to the brain, due to thrombotic (local blood clot formation) or embolic (due to a blood clot or other material traveling from another site) event. "Noteworthy, a marked upregulation of GPR17 expression in OPCs close to demyelinated sites has been observed in several mouse models of central nervous system injury, including ischaemic stroke." (PMID 39703181, 2025). "We envisage that these data will aid the development of GPR17‐targeted regenerative approaches for treating ischaemic stroke." (PMID 39703181, 2025). "To define the cellular identity and differentiation stage of GPR17‐expressing cells in human ischaemic stroke lesions, we performed double immunofluorescence labelling for GPR17 and markers of different OL maturation stages and other neuronal and glial cells." (PMID 39703181, 2025). "We found that the relative expression level of GPR17 in ischemic stroke patients was significantly lower than that in normal participants (p < 0.01)." (PMID 34483854, 2021). "In this respect, the pharmacological inhibition of GPR17 by montelukast (a drug already known for its anti‐asthmatic effect) was shown to reduce the extent of damage and restore brain connectivity and remyelination in ischaemic stroke mice." (PMID 39703181, 2025). "Hence, these data strengthen the relevance of GPR17‐based remyelinating therapies for the treatment of ischaemic stroke." (PMID 39703181, 2025). "Regulatory axis, such as SND1-IT1/NAPA-AS1/LINC01001-miR-24-3p-LPAR3/ADORA1 and LUCAT1/ASAP1-IT2-miR-93-3p-GPR17 may play important roles in the progression of ischemic stroke." (PMID 34483854, 2021). "lncRNA-miRNA-mRNA regulatory axis such as SND1-IT1/NAPA-AS1/LINC01001-miR-24-3p-LPAR3/ADORA1 and LUCAT1/ASAP1-IT2-miR-93-3p-GPR17 may play important roles in the progression of ischemic stroke." (PMID 34483854, 2021). "Thus, we speculated that miR-93-3p may be involved in the progression of ischemic stroke by regulating GPR17." (PMID 34483854, 2021). "In this respect, previous studies highlighted the role of the G protein‐coupled membrane receptor 17 (GPR17) as a key regulator of OPC differentiation in experimental models of brain injury, including ischaemic stroke." (PMID 39703181, 2025). "In conclusion, LPAR3, ADORA1, GPR17, and OPRM1 may serve as therapeutic targets of ischemic stroke." (PMID 34483854, 2021). "LPAR3, ADORA1, GPR17, and OPRM1 may serve as therapeutic targets of ischemic stroke." (PMID 34483854, 2021).
Sepsis (3 papers, 2021 to 2024). Sepsis is defined as life-threatening organ dysfunction caused by a dysregulated host response to infection. "Recently, the inhibition of GPR17 in mouse models using Cangrelor, an antagonist anti-platelet drug, was associated with a significant decrease in the inflammatory response injury and pulmonary fibrosis during sepsis." (PMID 38856841, 2024). "The levels of GPR17 in the lung tissue were significantly higher (p<0.05) in the sepsis group compared to the sham group." (PMID 37675176, 2023). "The study demonstrated that the Ticagrelor-treated group exhibited a greater decrease in the tissue lung levels of GPR17 compared to the sepsis and vehicle groups." (PMID 37675176, 2023). "The study found significantly increased tissue levels of GPR17 in the lung tissue of the sepsis and vehicle groups compared to the sham group." (PMID 37675176, 2023). "However, the Ticagrelor-treated group showed significantly decreased GPR17 expression compared to the sepsis group." (PMID 37675176, 2023). "Our study indicated that cangrelor repressed the levels of GPR17, followed by a decrease in the inflammatory response and a rise of neutrophils in BALF, potentially reversing CLP-mediated pulmonary injury during sepsis." (PMID 34229761, 2021). "Our study suggested that cangrelor inhibited the expression of GPR17 in lung tissue, thus attuned the inflammatory response and the recruitment of neutrophils in BALF, and ameliorated CLP-mediated pulmonary injury during sepsis." (PMID 34229761, 2021).
asthma (2 papers, 2021 to 2023). "Interestingly, the defective differentiation of OPCs isolated from the spinal cord of the SOD1G93A mutant mice was rescued by treatment with the GPR17 antagonist montelukast (a leukotrien receptor antagonist authorized for the management of asthma)." (PMID 33810425, 2021). "Montelukast (MLK) is a cysteinyl leukotriene receptor 1 (CysLT1R) and G protein-coupled receptor 17 (GPR17) antagonist, approved as adjuvant therapy for asthma in both children and adults." (PMID 36782185, 2023).
astrocytoma (2 papers, 2008 to 2021). "For GPR17, its expression was more confined to OLIG1+ cells in the oligodendroglioma, whereas a similar expression was found in the SOX9+ and OLIG1+ subpopulations in the explored astrocytoma." (PMID 33925547, 2021). "The plasmid containing the positive murine GPR17 clone (pcDNA3.1-Gpr17m) was used to transiently transfect 1321N1 human astrocytoma cells, a cell line lacking endogenous P2Y receptors and already utilized for the characterization of human and rat GPR17." (PMID 18974869, 2008).
diabetes (2 papers, 2024 to 2025). "Through validation on null intestinal organoids, it was found that inhibition of intestinal Gpr17 expression could promote GLP-1 secretion and thus improve glucose metabolism, suggesting that GPR17 may be a potential interventional target for the treatment of diabetes mellitus." (PMID 40926989, 2025).
Insulin resistance (2 papers, 2021). Increased resistance towards insulin, that is, diminished effectiveness of insulin in reducing blood glucose levels. "Intracerebroventricularly-administered agonists of G protein-coupled receptor 17 (GPR17) stimulate and antagonists inhibit feeding, with the agonists promoting insulin resistance in response to high fat diet." (PMID 34646232, 2021).
pulmonary fibrosis (2 papers, 2023 to 2024). Chronic progressive interstitial lung disorder characterized by the replacement of the lung tissue by connective tissue, leading to progressive dyspnea, respiratory failure, or right heart failure. "Cangrelor, a GPR17 antagonist, has been shown to inhibit GPR17 signaling, and reduce pulmonary fibrosis by inhibiting GPR17-mediated inflammation in mice." (PMID 37990234, 2023).
schizophrenia (2 papers, 2012 to 2025). A major psychotic disorder characterized by abnormalities in the perception or expression of reality. "About half of them has been previously associated with schizophrenia in humans, such as Olig1, Fgfr1, Gpr17, Gna12, Abca2, Sox1, Dpm2, and, as a locus for de novo mutations, Rab2a." (PMID 39825014, 2025). "An RNA sequencing analysis of the PFC suggested a dysregulation of numerous schizophrenia related genes including Olig1, Fgfr1, Gpr17, Gna12, Abca2, Sox1, Dpm2, and Rab2a in the rat model of psychosis." (PMID 39825014, 2025).
brain infarct (1 paper, 2008). "Magnetic Resonance Imaging in living mice showed that the in vivo pharmacological or biotechnological knock down of GPR17 markedly prevents brain infarct evolution, suggesting GPR17 as a mediator of neuronal death at this early ischemic stage." (PMID 18974869, 2008).
chronic rhinosinusitis (1 paper, 2021). Chronic form of sinusitis. "However, even though GPR17 expression has not been confirmed on eosinophils yet, a recent report describes higher GPR17 expression in nasal polyp tissue in eosinophilic versus non-eosinophilic chronic rhinosinusitis, suggesting its involvement in eosinophil infiltration." (PMID 33919453, 2021).
diffuse midline glioma (1 paper, 2021). A diffuse glioma that arises from the midline structures of the central nervous system. "GPR17 clustering is associated with the overexpression of transcription factors such as Olig1 and Olig2 in pediatric diffuse midline glioma (pDMG), with the aborted differentiation of the oligodendrocytic lineage of the cells." (PMID 34359676, 2021).
Glucose intolerance (1 paper, 2021). Glucose intolerance (GI) can be defined as dysglycemia that comprises both prediabetes and diabetes. "In summary, compared to wild-type mice, GPR17 -/- mice of the 129 strain displayed increased expression of UCP-1 in white adipose tissue, lower body weight and fat content, and resistance to HFD-induced glucose intolerance." (PMID 34646232, 2021).
infarction (1 paper, 2014). A localised pathological necrosis of tissue resulting from obstruction of the blood supply usually by a thrombus, an embolus, or vascular torsion. "The appearance in the ischaemic myocardium of GPR17+/Iso-B4+ and GPR17+/Sca-1− cells suggested that the receptor characterizes also a circulating inflammatory cells population recruited at short time after infarction." (PMID 24909956, 2014).
low grade glioma (1 paper, 2021). A grade I or grade II glioma arising from the central nervous system. "Our dataset analysis revealed constitutive expression of GPR17 in low-grade glioma (LGG) and GBM, where its expression is not only linked with improved survival but also significantly associated as a predictive biomarker." (PMID 34359676, 2021).